IL4 (interleukin 4)
Diseases named in the same sentence as IL4 in open-access papers (continued):
Sharing a sentence is not in itself a finding about the gene and the disease.
Insulin resistance (continued). "The progression of metabolic abnormalities would be possible to reverse if an appropriate intervention was adopted, e.g., OW administration in the present study or IL-4 to restore energy metabolic efficiency and attenuate adipose/hepatic adiposity before systemic insulin resistance is developed." (PMID 32752112, 2020). "Except for directly participating in the regulation of lipid metabolism, microenvironmental IL-4 may antagonize chronic inflammation in adipose tissues once insulin resistance is occurred." (PMID 31427606, 2019). "While the M1 phenotype stimulates the generation of inflammatory cytokines such as TNF-α, iNOS, CCR2, and IL-12, the M2 phenotype promotes anti-inflammatory cytokines like IL-4 and IL-13, which relieve inflammatory reactions and inhibit the development of insulin resistance." (PMID 31212747, 2019). "In the present study, we reveal that IL-4 promotes myogenesis and improves glucose metabolic efficacy in muscle cells, which further suggest that IL-4 has dual potential to act as an adjuvant therapeutic target for sarcopenia and insulin resistance." (PMID 31814802, 2019). "IL-4, a major immunoregulatory factor secreted by Th2 cells, plays an important role in protecting pancreatic β cells, reducing the inflammation level in insulin target organs and thus alleviating insulin resistance." (PMID 29713241, 2018). "Indeed, myeloid cell-specific Irs2-deficient mice show impairment of IL-4-induced M2a-subtype macrophage activation, as a result of stabilization of the FoxO1/HDAC3/NCoR1 corepressor complex, resulting in insulin resistance under the HF diet condition." (PMID 30451856, 2018). "Additionally, these observations support our speculation that IL-4 harbors the activity to attenuate the development of insulin resistance and the subsequent progression to metabolic abnormalities." (PMID 31427606, 2019). "The ZS-Ag-NPs treatment significantly decreased insulin resistance and metabolic inflammation-related LTB4-R, TNF-α, IL-4 and STAT-6 mRNA levels." (PMID 34685001, 2021). "The pathophysiological and immunological mechanisms linking increased serum levels of IL-4 and the occurrence of T2DM, metabolic control, and insulin resistance are still unclear." (PMID 29713241, 2018). "Regulatory cytokines such as interleukin (IL)-4 and -10 produced by AT iNKT cells prevented the development of DIO and insulin resistance even in mice fed a low-fat diet." (PMID 29942311, 2018). "The administration of IL-4 to mice induces M2 activation of macrophages, thereby attenuating HFD-induced insulin resistance." (PMID 23964268, 2013). "For IL13, we found a significant inverse correlation to body weight, body fat, and waist circumference, whereas IL4 expression inversely correlated with waist circumference, fasting plasma glucose (FPI), and homeostatic model assessment for insulin resistance (HOMA-IR) in visceral WAT." (PMID 36982747, 2023). "In addition, brown adipose tissue releases pro-inflammatory mediators such as IL-8, IL-4, IL-1, IL-6, TNF-α, and histamine in response to high blood glucose levels and improved insulin resistance." (PMID 37241737, 2023). "Chemerin levels were directly and strongly correlated with IL-10 (r = 0.41) and interleukin-4 (r = 0.50) and inversely correlated to insulin resistance index (r = −0.23) in GDM but not NGDM." (PMID 34007846, 2021). "Curcumin improved peripheral insulin resistance in insulin-resistant ob/ob mice with steatosis by reducing NF-κB/RelA DNA-binding activity, decreasing mRNA level of TNF and IL-6, and enhancing IL-4 production in hepatic TNF/iNOS-producing dendritic cells and adipose tissue macrophages." (PMID 24348712, 2013). "IL-4 influences lipid metabolism via STAT6, promoting adipogenesis, lipolysis, and reducing leptin levels, thereby improving insulin resistance or inducing white adipose browning in the absence of leptin." (PMID 41007770, 2025).
Insulin resistance (continued). "Furthermore, the analysis of condition media showed the absence of insulin resistance and immune cell-attracting inflammatory markers, such as LTB4, STAT-6, IL-4 and TNF-α levels." (PMID 32235695, 2020).
ischemic stroke (49 papers, 2012 to 2026). A stroke disorder caused by obstruction of blood flow to the brain, due to thrombotic (local blood clot formation) or embolic (due to a blood clot or other material traveling from another site) event. "We found that genetically predicted IL-4 levels were negatively associated with ischemic stroke, which adds to epidemiological evidence to the role of inflammatory factor-targeted drug therapy in the prevention and treatment of ischemic stroke." (PMID 35111052, 2021). "Studies on the IL-4 gene polymorphism provide some valuable information concerning prognosis for patients with different types of ischemic stroke and related complications." (PMID 31701356, 2020). "Besides, our study confirmed that increased IL-4 was associated with a reduced risk of ischemic stroke." (PMID 35111052, 2021). "Furthermore, IL-4 gene polymorphisms are related to susceptibility to ischemic stroke and subsequent functional outcomes." (PMID 31226122, 2019). "For example, IL-4 deficient mice display less long-term functional recovery after ischemic stroke." (PMID 28785217, 2017). "The risk of ischemic stroke can be influenced by genetic variation in the inflammatory agents, including Interleukin-33 (IL-33), interleukin 4 (IL-4), interleukin 6 (IL-6), intercellular adhesion molecule 1 (ICA M-1), E-selectin (E-sel), chemokine (C-C motif) ligand 11 (CCL11), lymphotoxin (LTA)." (PMID 24107076, 2013). "Among these, anti-inflammatory cytokines, particularly, interleukin-13 (IL-13) and Interleukin-4 (IL-4), delivered via the intranasal route, were reported to promote white matter recovery in ischemic stroke." (PMID 41304786, 2025). "IL‐4 is crucial for the polarization of microglial cells and recovery of neurons after an ischemic stroke." (PMID 41395456, 2025). "We aimed to investigate the association between serum levels of selected cytokines (IL-1β, IFN-γ, IL-4), and vitamin D in ischemic stroke progression, and their accuracy in predicting AIS prognosis, among Sri Lankans." (PMID 38870172, 2024). "Interleukins such as TNF-α, IL-2, IL-4, IL-6 and IL-10, secreted by lymphocytes, play an important role in the pathogenesis and prognosis of ischemic stroke." (PMID 39204113, 2024). "On the other hand, IL-4 is believed as an anti-inflammatory cytokine in many pathological conditions and plays a protective role against ischemic stroke." (PMID 36782269, 2023). "Neurons produce IL-4 after an ischemic stroke and the expression of IL-4 receptors (IL-4Rs) on microglia increases in response." (PMID 36793730, 2023). "Li's study showed that the serum IL-4, IL-5, IL-7, and IL-9 levels decreased in the ischemic stroke patients with poor outcome." (PMID 36875689, 2023). "It has been reported that infarct size after an ischemic stroke can be reduced by IL-4 secreted by M2 microglia and can contribute to recovery postmortem." (PMID 38089678, 2023). "Long-term healing after an ischemic stroke and microglia/macrophage M2 polarization depend heavily on IL-4." (PMID 36793730, 2023). "Our data show that 2′-FL reduced the neurological symptoms of ischemic stroke and ROS accumulation in the brain through IL-4/STAT6-dependent M2-type microglial polarization in MCAO mice." (PMID 37372011, 2023). "Consistent with the network pharmacology findings, in the current study, it is revealed that IL-1β, TNF-α, IL-6, and IL-4 were significantly increased in the cerebral cortex and hippocampus after ischemic stroke." (PMID 36338345, 2022). "Our recent study demonstrated that pro-inflammatory monocytes migrate shortly after an ischemic stroke and are converted by interleukin (IL)-4 and IL-13 into anti-inflammatory macrophages that attenuate ischemic stroke." (PMID 35634277, 2022). "IL-4 plays an important role in the M2 polarization and long-term recovery of microglia/macrophages after ischemic stroke." (PMID 35173738, 2022).
ischemic stroke (continued). "Of these, the importance of IL-4 for restoration of neurological function in pathological conditions, including ischemic stroke, has been well documented." (PMID 35887140, 2022). "An upregulation of TNF-alpha, IL-1beta, and IL-4 gene expression was found in total monocytes 24 and 48 h after an ischemic stroke compared to healthy conditions." (PMID 34201498, 2021). "The possible explanation is that the anti-inflammatory factor IL-4 acts by binding to the IL-4 receptor, enhancing the IL-4 signaling pathway, reducing the incidence of ischemic stroke, and promoting recovery after ischemic stroke." (PMID 35111052, 2021). "For example, administration of IL-4, a cytokine released after an injury from challenged neurons enhances microglial phagocytosis of AC supporting brain cleanup after an ischemic stroke that translates to better outcomes and decreased lesion volume." (PMID 33925299, 2021). "The polarization of M2 microglia commenced several days after ischemic stroke and was induced by IL-4, IL-10, vascular endothelial-derived growth factor (VEGF), and GSF secreted from neurons." (PMID 34248961, 2021). "Changes of the IL-4 serum concentration, together with increase of the IL-6 serum levels, have been reported as diagnostically valuable in the acute phase of ischemic stroke." (PMID 31701356, 2020). "Previous preclinical studies have similarly documented therapeutic effects of low doses of IL-4 in ischemic stroke and other neurological diseases." (PMID 31226122, 2019). "Studies have found that the expression levels of IL-4, IL-5, IL-6, and IL-10 are increased remarkably in the damaged hemisphere after ischemic stroke." (PMID 31164999, 2019). "IL-4 mRNA generates as early as 1 h, reaches a peak at 3–24 h, and gradually declines 2 d following ischemic stroke." (PMID 27703487, 2016). "Available evidence indicates that CeAD accompanied by ischemic stroke is associated with higher plasma levels of hepatocyte growth factor (HGF) and stromal cell-derived factor 1α (SDF-1α) as well as lower IL-4 concentrations, reflecting a more pronounced systemic inflammatory activation." (PMID 41570020, 2026). "Furthermore, individuals receiving edaravone dexborneol injection exhibited lower expression levels of interleukin (IL)-1β, IL-6, and IL-17, along with higher levels of IL-4 and IL-10 expression during the acute phase of ischemic stroke (P < 0.05)." (PMID 38902691, 2024). "IL-4-polarized microglia cells may alleviate the ischemic stroke injury by promoting angiogenesis through the secretion of exosomes containing miRNA-26a." (PMID 35173738, 2022). "Furthermore, IL-4 secreted by microglia M2 decreased the size of the infarction after ischemic stroke and improved long-term functional recovery." (PMID 35055089, 2022). "Moreover, the KEGG Mapper results further showed that IL-1β, TNF-α, IL-6, and IL-4 are core potential targets involved in Epimedium-mediated neuroinflammation following ischemic stroke." (PMID 36338345, 2022). "After ischemic stroke, IL-4 treatment has been shown to enhance white matter integrity." (PMID 35173738, 2022). "However, IL-4 and IL-13 levels continued to be higher than those of the other cytokines on days 3 and 7 after ischemic stroke." (PMID 33409730, 2021). "However, the potential effects of IL-4 on white matter integrity after ischemic stroke remain elusive." (PMID 31226122, 2019). "These collective findings suggest that activation of the IL-4/PPARγ signaling cascade may represent a novel recovery-enhancing strategy to promote long-term outcomes after ischemic stroke." (PMID 31226122, 2019). "In light of these results, we evaluated whether IL-4 influenced white matter integrity after ischemic stroke." (PMID 31226122, 2019). "Therefore, it seems reasonable to continue to test IL-4 as a therapeutic strategy for functional recovery after ischemic stroke." (PMID 31226122, 2019).
ischemic stroke (continued). "Interestingly, IL-4 knockout mice had a larger infarct volume and poorer neurological outcome after ischemic stroke." (PMID 22707991, 2012). "Epimedium treatment significantly inhibited the expression of IL-1β, TNF-α, and IL-6 and enhanced the expression of IL-4, which suggests that Epimedium exerted its neuroprotective effects via regulating the expression of proinflammatory and anti-inflammatory cytokine following ischemic stroke." (PMID 36338345, 2022). "Moreover, IL-4 promotes long-term recovery after ischemic stroke." (PMID 27703487, 2016). "For example, the IL-4/STAT6 pathway is one of the canonical pathways of hemorrhage clearance in the brain and STAT6 signaling is activated also after the ischemic stroke." (PMID 33925299, 2021). "In clinical practice focusing on prognostic indicators for ischemic stroke patients found that there was a close negative correlation between IL-10 and NIHSS scores (P=0.0006), but not between IL-4 and NIHSS scores (P=0.088)." (PMID 40134421, 2025).
multiple sclerosis (49 papers, 2007 to 2026). A progressive autoimmune disorder affecting the central nervous system resulting in demyelination. "As IL-10 has been found to be associated with a less pathogenic phenotype of Th17 cells in the mouse model of multiple sclerosis, we evaluated IL-10 responses in mice that received neutralizing antibodies to IL-4 and/or IFN-γ." (PMID 19852819, 2009). "While the discovery that IL-4 was positively associated with cognitive development was surprising, a beneficial effect of IL-4 on the CNS has support from human studies of the inflammatory disease multiple sclerosis." (PMID 24548288, 2014). "Most of the resulting pathways involved aspects of inflammation: cytokine pathways (“IL-4 signaling”, “IL-10 signaling” and “IL-12 signaling”), “Multiple Sclerosis Signaling Pathway”, “Pathogen Induced Cytokine Storm Signaling Pathway” and “Complement system”." (PMID 38321224, 2024). "In contrast, IL-4 exerts an anti-inflammatory effect that suppresses the development multiple sclerosis in mouse models." (PMID 39011048, 2024). "Some studies also found that the IgG index correlated with CSF IL-4 levels in patients with multiple sclerosis." (PMID 35145923, 2021). "OCH is a glycolipid antigen and a ligand of iNKT cells that promotes IL‐4 secretion, and it has been tested in clinical trials for the treatment of Crohn's disease and multiple sclerosis." (PMID 34214248, 2021). "Several studies have indicated that IL-4 can influence the progression of neurological diseases, such as Alzheimer’s disease, multiple sclerosis, and glioblastoma multiforme." (PMID 32635653, 2020). "Vogelaar and colleagues reported that intrathecal or intranasal (1 μg/d) IL-4 treatment ameliorated clinical signs and reversed disease progression in a model of multiple sclerosis." (PMID 31226122, 2019). "Further, in tissue culture experiments and in the experimental autoimmune encephalomyelitis (EAE) model of multiple sclerosis, treatment of microglia/macrophages with IL-4 promoted the generation of oligodendrocytes." (PMID 31839002, 2019). "This is in line with a recent study showing that microglial EVs engineered to deliver an anti-inflammatory cytokine IL-4 induce a long-lasting immune modulation in the EAE model of multiple sclerosis." (PMID 31363836, 2019). "CNS-derived IL4 has been further shown to play important roles during regulation of microglia/macrophage activation in the EAE model for multiple sclerosis." (PMID 28337124, 2017). "We thus next investigated this possibility in a small cohort of samples from healthy controls or individuals with either multiple sclerosis (MS) or Spondylarthritis (SpA) using M0 (unstimulated), M1 (LPS/IFNγ) or M2 (IL-4/IL-10/TGF-β) polarization protocols." (PMID 24521472, 2014). "It was also shown that IL-4 delayed pathology progression in an experimental model of multiple sclerosis and promoted oligodendrogenesis." (PMID 23404620, 2013). "The role of IL-4 in regulating CNS inflammation was also investigated in experimental autoimmune encephalomyelitis, a mouse model for multiple sclerosis." (PMID 21909267, 2011). "Sexual hormones especially testosterone promotes IFN-γ production from CD4 cells isolated from multiple sclerosis patients and estradiol promotes IL-4 cytokines in spleen cells of C57BL/6 mice." (PMID 23675060, 2008). "The RT–qPCR results indicated an increase in gene transcripts in TG mice of pro- and anti-inflammatory cytokines, with a significant influence of IFN β treatment on the reduction of IL4 expression, corroborating previous studies carried out in multiple sclerosis models." (PMID 37711512, 2023). "IL4-induced M2-like microglia/macrophage activation has been described to exert neuroprotective effects in mouse models for spinal cord injury, cerebral ischemia and multiple sclerosis." (PMID 28337124, 2017).
multiple sclerosis (continued). "However, it is generally accepted that multiple sclerosis is primarily a Th1 disease, although a recent clinical study has demonstrated that patients with progressive multiple sclerosis as well as relapsing-remitting patients have increased IL-4 levels." (PMID 31839002, 2019). "Also, adoptive transfer of monocytes carrying CAMPs encapsulating IL‐4 and dexamethasone enabled persistent conversion of their phenotypes to anti‐inflammatory type, which allowed for modulation of both the brain and systemic immune responses and treatment of multiple sclerosis." (PMID 39801750, 2025). "In fact, IL-4, IL-10, and IL-13 high levels promote enhanced axonal regeneration, promote neuroprotection after SCI, and reduce demyelination in multiple sclerosis." (PMID 31186006, 2019). "Together the data support the late effects of vitamin D on diseases like inflammatory bowel disease and multiple sclerosis where reducing IL-17 and IFN-γ, while inducing IL-4 and IL-10, would be beneficial." (PMID 25912039, 2015). "In CD4 cells, PGJ2 and the TZD ciglitazone reduced IL4 production and in EAE, the animal model of Multiple Sclerosis, PGJ2 blocked splenic T cell production of IL10 and IL4." (PMID 17207275, 2007). "In Multiple Sclerosis (MS), CBD in preclinical models of MS resulted in a reduction of proinflammatory cytokines such as IL-17A, IFN-γ, TNF-α, IL-6 and IL-1b and an increase in anti-inflammatory cytokines such as IL-4, IL-10 and TGF-β." (PMID 38601151, 2024). "The therapeutic potential of exogenous IL4 has been well documented in several CNS pathology models including models for spinal cord injury, APP/PS1 transgenic mice, cerebral ischemia as well as multiple sclerosis." (PMID 28337124, 2017). "To ensure the in vivo suppressive potential of systemic administration of the IL-4-activated BMDM, we used a mouse model of multiple sclerosis, which represents an inflammatory T-cell mediated CNS disease that can be arrested by systemic anti-inflammatory treatment." (PMID 22073221, 2011).